PRCP (prolylcarboxypeptidase)
Description:
Cleaves C-terminal amino acids linked to proline in peptides such as angiotensin II, III and des-Arg9-bradykinin. This cleavage occurs at acidic pH, but enzymatic activity is retained with some substrates at neutral pH.
Synonyms: PCP; HUMPCP
Tractability: Small molecule: a high-quality ligand is known; it has a high-quality binding pocket; it belongs to a druggable protein family. Antibody: its Gene Ontology location is reachable by antibodies, with high confidence; UniProt predicts a signal peptide or a membrane-spanning region. PROTAC: ubiquitination databases record sites on it; its protein half-life has been measured; a small molecule that binds it is known.
Target class: Enzyme; Serine protease S28 family; Serine protease SC clan; Protease; Serine protease
Gene: Protein-coding gene on chromosome 11 (82,822,936 to 82,970,584, reverse strand). Ensembl gene ENSG00000137509.
Subcellular location: Lysosome
Subcellular location (Human Protein Atlas): Vesicles
Pathways (Reactome):
Immune System: FXIIa activates plasma kallikrein-kinin system; Neutrophil degranulation
Gene Ontology:
Molecular function: protein binding; serine-type carboxypeptidase activity; carboxypeptidase activity; metallocarboxypeptidase activity; serine-type exopeptidase activity
Biological process: angiogenesis involved in wound healing; negative regulation of systemic arterial blood pressure; regulation of blood vessel endothelial cell migration; angiotensin maturation; proteolysis
Cellular component: extracellular exosome; azurophil granule membrane; ficolin-1-rich granule membrane; lysosome; plasma membrane; basal part of cell; extracellular region
Genetic constraint (gnomAD): Loss-of-function variants: 40 observed, 46.55 expected, observed/expected ratio (o/e) 0.86, 90% interval 0.67 to 1.12. The upper end of that interval is the gene's LOEUF score, 1.12, which puts it in group 4 of 6, group 1 being the genes least tolerant of losing a copy. Missense variants: 568 observed, 549.93 expected, observed/expected ratio (o/e) 1.03, 90% interval 0.96 to 1.11. Synonymous variants: 225 observed, 196.65 expected, observed/expected ratio (o/e) 1.14, 90% interval 1.02 to 1.28.
Homologues: Orthologues: chimpanzee PRCP (99% identical), macaque PRCP (98% identical), rabbit PRCP (84% identical), dog PRCP (80% identical), pig PRCP (80% identical), guinea pig PRCP (78% identical), rat Prcp (77% identical), mouse Prcp (77% identical), tropical clawed frog smyd2 (63% identical), zebrafish prcp (59% identical), Drosophila melanogaster CG2493 (44% identical), Caenorhabditis elegans pcp-5 (39% identical). Paralogues in human: DPP7 (41% identical), PRSS16 (24% identical).
Diseases named in the same sentence as PRCP in open-access papers:
PRCP is named in the same sentence as 41 diseases in open-access papers, as found by Europe PMC text mining. Sharing a sentence is not in itself a finding about the gene and the disease. The quoted sentences say what the papers report.
Hypertension (8 papers, 2009 to 2026). The presence of chronic increased pressure in the systemic arterial system. "Both NT5C2 and PRCP were involved in blood pressure regulation, with the PRCP polymorphism (E112D) associated with hypertension and NT5C2 correlated with elevated blood pressure." (PMID 40346920, 2025). "While the PRCP gene variant affects the progression of hypertension, its depletion results in vascular dysfunction and faster arterial thrombosis in mice." (PMID 38792081, 2024). "Targeting NT5C2 and PRCP appeared safe and exclusively effective for IA, including ischemic stroke and hypertension." (PMID 40346920, 2025). "Targeting NT5C2 and PRCP appeared exclusively effective and safe for IA, including ischemic stroke and hypertension, which warranted future investigations." (PMID 40346920, 2025). "Model selection for the best fit for the association between SNP rs7104980 (PRCP gene) and SNP rs3733402 (KLKB1 gene) with hypertension and a history of diabetes, cigarette use, or angina." (PMID 27200353, 2016). "Prolylcarboxypeptidase (PRCP) dysfunction is associated with adverse cardiovascular consequences such as inflammation and hypertension." (PMID 19171072, 2009). "Its relevance for renal homeostasis is supported by findings that renal PRCP expression is reduced in hypertensive rats and restored by losartan, and that PRCP depletion in mice induced endothelial dysfunction, hypertension, alterations in renal and vascular eNOS, and increased ROS formation." (PMID 41511943, 2026). "Having the G allele compared to not having the G allele for rs7014980 (PRCP gene) increased the odds of having hypertension and a history of angina by 22% [OR = 1.220; 95% CI = (1.016, 1.467)]; P = 0.034, but this analysis was not statistically significant (P > 0.01) after Bonferroni correction." (PMID 27200353, 2016). "PRCP can inactivate a number of peptide hormones, such as angiotensin II, III and prekallikrein, implicating a role for the enzyme in hypertension, tissue proliferation and smooth-muscle growth." (PMID 20598110, 2010).
Obesity (6 papers, 2018 to 2025). Accumulation of substantial excess body fat. "For example, PRCP deficient mice exhibit reduced food intake and resistance to diet-induced obesity due to elevated α-MSH levels." (PMID 30305673, 2018). "Study had demonstrated that PRCP plays a crucial role in the onset and progression of obesity, regulating the balance between energy intake and expenditure through an α-MSH1-mediated mechanism." (PMID 41221287, 2025). "A link between serum PRCP activity and obesity has been reported, but its origin/source is still unclear." (PMID 36362314, 2022). "In humans, different studies were conducted investigating PRCP protein and activity levels in obesity, diabetes and cardiovascular dysfunction." (PMID 36362314, 2022). "Plasma PRCP protein levels were increased in patients with T2D and/or obesity and were significantly correlated with signs of obesity and diabetes and markers of lipid metabolism." (PMID 36362314, 2022). "PRCP KO mice consume significantly less food compared to controls and have been shown to be resistant to diet-induced obesity." (PMID 29772029, 2018). "The ratio of PRCP protein concentration to activity in serum could reflect the severity of obesity and sheds some much needed light on the possible additional source(s) of circulating PRCP." (PMID 29772029, 2018). "Gaining a greater understanding of PRCP’s multi-faceted biological functions could open up novel therapeutic avenues for the treatment of obesity." (PMID 29772029, 2018). "PRCP protein concentrations were also reported to be higher in patients with obesity or diabetes in comparison with healthy controls, but in patients with both obesity and diabetes, the PRCP plasma concentrations were significantly higher than in patients with obesity only." (PMID 36362314, 2022). "Previous study had shown that PRCP, through its involvement in the pro-opiomelanocortin (POMC) system, makes it a highly promising target in the treatment of obesity and related diseases." (PMID 41221287, 2025).
breast carcinoma (5 papers, 2015 to 2022). "We found high PRCP expression is associated with reduced overall survival in ER+/Her2- breast cancer patients and earlier recurrence in ER+/Her2- breast cancer patients treated with endocrine therapy." (PMID 36332175, 2022). "We found high PRCP protein levels in ER+ breast tumors associates with worse outcome and earlier recurrence in breast cancer patients, including patients treated with TAM." (PMID 36332175, 2022). "In the current report, we found high PRCP protein expression associates with worse outcome and earlier recurrence in breast cancer patients, including ER+ patients treated with TAM." (PMID 36332175, 2022). "To examine this, we first tested the effect of PRCP knockdown in ER+ MCF7 breast cancer cells using two different shRNAs." (PMID 36332175, 2022). "We previously found PRCP overexpression promoted 4-hydroxytamoxifen (4-OHT) resistance in estrogen receptor-positive (ER+) breast cancer cells." (PMID 36332175, 2022). "A small-molecule PRCP inhibitor blocked IGF1R/HER3 signaling in breast cancer cells, and enhanced the responsiveness of human ER+ breast cancer tumors in mice to endoxifen, an active metabolite of TAM." (PMID 36332175, 2022). "Taken together, the results support PRCP as a potential prognostic marker for outcome in breast cancer patients and a novel target to improve endocrine therapy in ER+ breast cancers." (PMID 36332175, 2022). "Thus, PRCP is an adverse prognostic marker in breast cancer and a potential target to improve endocrine therapy in ER+ breast cancers." (PMID 36332175, 2022). "Notably, PRCP KD in MCF7 (ER+) breast cancer cells also induced apoptosis and decreased proliferation and AKT phosphorylation." (PMID 35159006, 2022). "We tested the ability of the PRCP inhibitor to block growth of tumors formed by MDA468 (TNBC) cells and MCF7 cells, a human breast cancer line that is ER-positive and sensitive to tamoxifen." (PMID 35159006, 2022). "Overexpression of PRCP increased IGF1R/HER3 signaling and AKT-mTORC1 activation in ER+ breast cancer cells." (PMID 36332175, 2022). "We found PRCP increased IGF1R/HER3 signaling and AKT activation in ER+ breast cancer cells that was blocked by PRCPi." (PMID 36332175, 2022). "To examine a role for PRCP in TNBC, we created a 197 sample tissue microarray (duplicate cores) from breast cancer patients treated at Rush from 2000–2005 and for whom long-term follow-up data is available." (PMID 35159006, 2022). "Exosomal WNT11 binds frizzled (FZD)-disheveled segment polarity protein 1 (DVl) receptors to activate the WNT-prolylcarboxypeptidase (PCP) pathway, resulting in enhanced breast cancer cell protrusive activity, motility, and metastatic potential." (PMID 34671013, 2021). "In addition, we found that high expression of PRCP correlates with increased expression of IGF1/NRG1 and their target genes and earlier recurrence of endocrine treated ER+ breast cancer patients." (PMID 36332175, 2022).
atherosclerosis (2 papers, 2018 to 2022). A disease characterized by the build-up of fatty material and calcium deposition in the arterial wall resulting in partial or complete occlusion of the arterial lumen. "Finally, we found proteins related to atherosclerosis and aberrant hemostasis, including PRCP and SERPINA5." (PMID 35945262, 2022). "Hence, pharmacological means to increase α-MSH bioavailability, e.g. via inhibition of PRCP, could provide a therapeutic strategy to treat atherosclerotic cardiovascular disease, but future mechanistic experiments will be instrumental to clarify the role of PRCP in atherosclerosis." (PMID 30305673, 2018).
coronary artery disease (2 papers, 2018 to 2024). "Since polymorphisms of the PRCP gene have been related to metabolic syndrome among coronary artery disease patients, we also categorized the patients based on metabolic syndrome." (PMID 29772029, 2018).
endothelial dysfunction (2 papers, 2018 to 2026). In vascular diseases, endothelial dysfunction is a systemic pathological state of the endothelium (the inner lining of blood vessels) and can be broadly defined as an imbalance between vasodilating and vasoconstricting substances produced by (or acting on) the endothelium. "On the other hand, endothelial dysfunction, as observed in obese patients, may also lie at the basis of the raised PRCP protein concentrations in plasma, since PRCP has been shown to be located on the membrane of endothelial cells and to regulate endothelial cell growth." (PMID 29772029, 2018).
pancreatic cancer (2 papers, 2022). "Our lab reported that in pancreatic cancer cells PRCP maintains levels of IRS1, a protein involved in signaling downstream of IGF-1R and other RTKs." (PMID 35159006, 2022).
Sepsis (2 papers, 2020 to 2022). Sepsis is defined as life-threatening organ dysfunction caused by a dysregulated host response to infection. "Moreover, PRCP activity has been observed in these cell populations and elevated serum/plasma PRCP is already described in several diseases with an inflammatory component such as rheumatoid arthritis, stroke and sepsis." (PMID 36362314, 2022).
viral infection (2 papers, 2013 to 2021). "In summary, it was demonstrated that TbCSV infection in N. benthamiana reduced the expression of nbe-miR167b-3p, which targeted PRCP genes to regulate plant development and enhanced defense of the plants against virus infection." (PMID 34975814, 2021). "However, the functions of the PRCP gene in plant responses to virus infection still remain unknown." (PMID 34975814, 2021). "Although it has not been clearly established how PRCP or HSP90 activates PK, we considered whether viral infection might increase the levels of these proteins and lead to increased PK activation." (PMID 23874198, 2013).
Age-related cataract (1 paper, 2021). A type of cataract (opacification of the lens) that forms during the course of aging. "Some of these genes associated with age-related cataracts include FRMD4B, NAALADL2, LOC105377670, LINC00968, LOC101929415, CTNNA3, LOC107984170, PRCP, and ZNF423, whereas others with a reduced risk include CFAP74, ACSL1, LOC101927668, LOC105369844." (PMID 34299682, 2021).
angioedema (1 paper, 2020). Swelling involving the deep dermis, subcutaneous, or submucosal tissues, representing localized edema. "The angioedema is due to bradykinin generated from high molecular weight kininogen by kallikrein, which is derived from plasma prekallikrein by action of the factor XIIa, factor Xia, or prolylcarboxypeptidase." (PMID 31984307, 2020).
Arterial thrombosis (1 paper, 2016). The formation of a blood clot inside an artery. "PRCP-deficient gene-trap (prcpgt/gt) mice that have 25% PRCP normal protein levels in their organs are constitutively hypertensive and have a heightened risk for arterial thrombosis." (PMID 27200353, 2016).
autoimmune optic neuritis (1 paper, 2024). An autoimmune form of optic neuritis. "To test this hypothesis, we first investigated the expression of PRCP in the optic nerves of mice with experimental autoimmune optic neuritis (EAON), a well-established animal model of demyelinating ON." (PMID 38610803, 2024).
glioblastoma (1 paper, 2009). The most malignant astrocytic tumor (WHO grade IV). "Importantly, PRCP, PTRF, LIMS1 and FSTL1 were expressed in the developing murine brain vasculature and are also overexpressed in glioblastoma, suggesting a role in tumor angiogenesis." (PMID 19924294, 2009). "The exact role of other vascular genes such as PRCP, LIMS1 and ENC1 in glioblastoma is not clear yet, but given their expression pattern, an implication in tumor angiogenesis is possible and merits further investigation." (PMID 19924294, 2009).
glomerular diseases (1 paper, 2017). "SHC1 and PRCP presented weak (+) staining in control kidney tissue and weak (+) to strong (+++) staining in the samples of other glomerular diseases and in the IgAN group." (PMID 28831120, 2017). "Immunohistochemistry staining for validation targets, CAP1, SHC1 and PRCP, was performed on eight IgAN, three other glomerular diseases and one healthy control slides of kidney tissue." (PMID 28831120, 2017).
insomnia (1 paper, 2025). A sleep disorder characterized by difficulty in falling asleep and/or remaining asleep. "The results indicated that PRCP and NT5C2 might play crucial roles in IA formation, even in cases of aSAH, when compared to SBP, smoking, and insomnia." (PMID 40346920, 2025).
invasive breast carcinoma (1 paper, 2022). A carcinoma that infiltrates the breast parenchyma. "First, we analyzed correlation between PRCP gene expression and IGF1 (IGF1R ligand) and NRG1 (HER3 ligand) expression in 1093 cases of invasive breast cancer (TCGA database) using TIMER software." (PMID 36332175, 2022).
ischemia (1 paper, 2020). A hypoperfusion of the BLOOD through an organ or tissue caused by a PATHOLOGIC CONSTRICTION or obstruction of its BLOOD VESSELS, or an absence of BLOOD CIRCULATION. "PRCP overexpression significantly increased mitophagy under ischemia but dampened mitophagy under reperfusion as compared with the Ad-Con group, whereas PRCP knockdown significantly decreased mitophagy under ischemia but exacerbated mitophagy under reperfusion as compared with the sh-Con group." (PMID 33195231, 2020). "PRCP activators or recombinant PRCP might be more meaningful for translational medicine than gene modification and be helpful to clarify the pathophysiological changes if PRCP is activated/upregulated after ischemia or reperfusion instead of prior to ischemia." (PMID 33195231, 2020).
metabolic syndrome (1 paper, 2018). A cluster of metabolic risk factors for CARDIOVASCULAR DISEASES and TYPE 2 DIABETES MELLITUS. "In parallel, we studied PRCP activity in serum of rats with metabolic syndrome." (PMID 29772029, 2018).
myocardial ischemia (1 paper, 2020). A disorder of cardiac function caused by insufficient blood flow to the muscle tissue of the heart. "The role of prolylcarboxypeptidase (PRCP) in myocardial ischemia/reperfusion (I/R) injury is unclear." (PMID 33195231, 2020).
preeclampsia (1 paper, 2016). Preeclampsia is a hypertensive disorder of pregnancy that is characterized by new-onset hypertension with proteinuria presenting after 20 weeks of gestation, and depending on mild or severe forms may initially present with severe headache, visual disturbances, and hyperreflexia. "An exon SNP of PRCP (rs2298668, E112D) indicates risk for chronic hypertension and preeclampsia in an African-American patient population." (PMID 27200353, 2016).
renovascular hypertension (1 paper, 2015). High blood pressure secondary to renal artery stenosis. "The progression of renovascular hypertension was associated with changes of renal PRCP expression and activity as analyzed using Western blot and mass spectrometry." (PMID 25706121, 2015).
schwannoma (1 paper, 2020). A benign, usually encapsulated slow growing tumor composed of Schwann cells. "Moreover, given the possible therapeutic efficacy of NSAIDs and curcumin against schwannomas, it is not surprising that PRCP, a mediator of inflammation and upstream regulator of angiotensin and bradykinin, was identified." (PMID 32848608, 2020).
metabolic disorders (5 papers, 2010 to 2025). "Prolyl carboxypeptidase (PRCP) is involved in metabolic disorders by hydrolyzing anorexigenic peptides." (PMID 36362314, 2022). "Prolyl carboxypeptidase (PRCP, EC 3.4.16.2), a lysosomal carboxypeptidase, is of interest in metabolic disorders due to its role in the C-terminal cleavage of α-melanocyte stimulating hormone (MSH) 1–13 and (pyr)-apelin-13." (PMID 36362314, 2022). "These novel findings on PRCP activity in serum support further investigation of its in vivo role and involvement in several metabolic diseases." (PMID 29772029, 2018). "These structural results provide the basis for rational design of selective PRCP regulators for the modulation of cardiovascular and metabolic diseases." (PMID 20540760, 2010). "A link between PRCP protein concentrations in plasma and metabolic disorders has been reported." (PMID 29772029, 2018).